EIF4E3 (eukaryotic translation initiation factor 4E family member 3)
Diseases named in the same sentence as EIF4E3 in open-access papers (continued):
Sharing a sentence is not in itself a finding about the gene and the disease.
tumor (30 papers, 2014 to 2025). "Whereas, overexpression of APOBEC3C and EIF4E3 in patients were associated with better survival, suggesting their potential role as tumor suppressor genes." (PMID 30881302, 2019). "The eIF4E family consists of three members; eIF4E3, the third, is thought to bind m7G-cap in an unusual way and have tumor-suppressive properties in cells." (PMID 40658715, 2025). "Co‐regulation of GRHL3 and EIF4E3, a putative tumor suppressor, was then verified by Spearman rank correlation in the TCGA BLCA data set (Spearman r = 0.257, P < 0.001)." (PMID 38429970, 2024). "In SCaBER, loss of ras homolog family member A (RHOA) GTPase activity was demonstrated to be associated with co‐regulation of eukaryotic translation initiation factor 4E family member 3 (EIF4E3), a potential tumor suppressor gene." (PMID 38429970, 2024). "According to one research, EIF4E3 depends on cap‐binding activity to operate as a tumour suppressor and compete with EIF4E's growth‐promoting capabilities." (PMID 38071502, 2024). "The m7GRGs AGO2, EIF4E3, DCPS and EIF4E have been extensively studied, and some of them have been associated with tumour progression." (PMID 37353728, 2023). "Lastly, 10 paired CRC tumor and paracancerous tissue samples were obtained, and qRT-PCR analyses revealed that EIF4E3 and GEMIN5 were downregulated in CRC, whereas NCBP2 was upregulated." (PMID 36482181, 2022). "The expression of CNV-amplified m7G regulators was markedly higher in HCC specimens than in normal control specimens, such as AGO2, NCBP2, GEMIN5 and LARP1, while the expression of EIF4E3 was significantly lower in tumor specimens." (PMID 36389726, 2022). "Eukaryotic translation initiation factor 4E family member 3 (EIF4E3) is a transformation initiating factor that can act as a tumor suppressor." (PMID 34926575, 2021). "EIF4E3 is downregulated in rapidly proliferating tumor cells, whereas EIF4E1 (formerly known as EIF4E) is abundantly expressed in tumor cells, although it is also present in most cells and plays an important role in angiogenesis." (PMID 32953883, 2020). "A study demonstrated that EIF4E3 relies on cap-binding activity to act as a tumor suppressor and compete with the growth-promoting functions of EIF4E." (PMID 30881302, 2019). "Taken together, our results suggested that miR-584-5p inhibits MB growth and progression by inhibiting the tumor-promoting function of HDAC1 or eIF4E3." (PMID 30382096, 2018). "MiR-584-5p imparts its tumor-suppressing and therapy-potentiating effects by targeting eIF4E3, HDAC1, and c-Myc in MB." (PMID 30382096, 2018). "In addition, a more established research model shows that eIF4E3 competes with eIF4E for the same transcriptional pool to inhibit the oncogenic capacity of eIF4E to drive tumour development." (PMID 41208200, 2025). "Since eIF4E3 inhibits mRNA export and translation targets of eIF4E1 and acts as a tumor suppressor, the increase in eIF4E3 in the PCB 126 proteome may affect the selected transcript translation." (PMID 34548932, 2021). "Our study shows a tumor-promoting and chemotherapy/IR-potentiating functions for eIF4E3 in MB." (PMID 30382096, 2018). "By regulating the translation of crucial transcription factors like n-Myc, eIF4E3 can also potentially upregulate the transcription of many pro-proliferative targets, which may contribute to the relapse of tumours treated with MNK or eIF4E1 inhibitors." (PMID 25403230, 2014). "Accordingly, the protein expression of EIF4E3, RPTOR, and AKT1S1 were all significantly associated with the MGPS, suggesting the elevated RNA translation efficiency led by EIF4EBP1_pT37 could promote tumor cell proliferation." (PMID 36434634, 2022). "Genes such as EIF4E3, IFIT5, EIF4G3, NUDT16, NUDT10, NCBP3, and NUDT11 showed lower expression in tumor tissues, whereas other genes were highly expressed." (PMID 41406096, 2025). "Only EIF4E3, IFIT5, EIF4G3, NUDT16, NUDT10, NCBP3, and NUDT11 showed decreased expression in tumor tissues." (PMID 41406096, 2025).
tumor (continued). "In fact, tumours that have increased EIF4E and low EIF4E3 expression demonstrate that EIF4E3 is of essential inhibitory mechanism that is lost in certain cancers." (PMID 38071502, 2024). "Numerous studies have found that m7G regulator hub genes (EIF4E, EIF4E3, EIF4E2, NCBP1, and NCBP2) are crucial in tumor progression and metastasis." (PMID 36998056, 2023). "Overexpression of EIF4E3 can induce the expression of CCL4/CCL5, playing a significant role in monocyte differentiation in the tumor microenvironment." (PMID 37664112, 2023). "MiR-584-5p mediated its tumor suppressor and therapy-sensitizing effects by targeting HDAC1 and eIF4E3." (PMID 30382096, 2018). "However, the higher expression levels of EIF4E3 and NUDT10 (both p < 0.001) were remarkably in normal tissues than those in tumor samples." (PMID 36118897, 2022). "However, there were a few downregulated genes in tumor samples, such as CYFIP1, IFIT5, DCP2, and EIF4E3." (PMID 36761423, 2022). "To determine whether miR-584-5p imparts its tumor-suppressing and VCR-sensitizing effect by downregulating HDAC1/eIF4E3 levels in MB, we first investigated the function of eIF4E3 and HDAC1 in MB." (PMID 30382096, 2018). "We show that miR-584-5p mediates its tumor suppressor and VCR/IR-potentiating effect by targeting eukaryotic translation initiation factor 4e family member 3 (eIF4E3) and histone deacetylase 1 (HDAC1), thereby affecting cell cycle progression, microtubule dynamics, and DNA damage response." (PMID 30382096, 2018). "Moreover, the other genes in the deletion, EIF4E3, RYBP, PROK2, and GPR27 all mediate activities that intersect with the PI3K pathway in a potentially tumor suppressive manner." (PMID 29057879, 2017). "EIF4E3 falls in between FOXP1 and RYBP, and is itself a purported tumor suppressor." (PMID 25155515, 2014). "Unlike eIF4E1, eIF4E3 functions as a tissue-specific tumour suppressor." (PMID 37353728, 2023).
cancer (14 papers, 2014 to 2025). A tumor composed of atypical neoplastic, often pleomorphic cells that invade other tissues. "In fact, reduced EIF4E3 levels in high-expressed EIF4E cancers suggests that EIF4E3 underlies a clinically relevant inhibitory mechanism that is lost in some malignancies." (PMID 30881302, 2019). "Compared to normal tissues, most genes were upregulated in cancer tissues, while EIF4E3, NUDT12, and NUDT4 were downregulated." (PMID 40018039, 2025). "The reduction in EIF4E3 in cancers with high EIF4E levels suggests that EIF4E3 is a clinically relevant inhibitory mechanism in some malignancies." (PMID 39940786, 2025). "The reduction of eIF4E3 in tumors of elevated eIF4E levels proposed that eIF4E3 identifies a related repressive mechanism in clinical disappearing into a few malignant tumors." (PMID 36118897, 2022). "It was reported that compared with patients with lower expression of EIF4E3, patients with high expression of EIF4E3 had markedly better survival rates in various cancers, including LUAD." (PMID 36091687, 2022). "Considering the latent roles of eIF4E3 in inhibiting eIF4E1 functions, these carcinomas seem to be motivated through the increase of eIF4E1 carcinogenic activities and the deletion of eIF4E3 inhibitory activities." (PMID 36118897, 2022). "EIF4E3 is a member of the eukaryotic translation initiation factor EIF4E family, which affects mRNA processing, nuclear export, translation and cancer development by specifically recognizing the 5′m7G cap structure of mRNA." (PMID 36532001, 2022). "What’s more, the expression of some writer genes (METTL1 and WDR4) and reader genes (AGO2 and NCBP2) was significantly upregulated in most cancers, while the expression of some eraser genes (NUDT12 and NUDT16) and some reader genes (EIF4E3) were downregulated in most cancers." (PMID 36339001, 2022). "In addition, we also explored the expression of AGO2, EIF4E3, DCPS and EIF4E in pan-cancer." (PMID 37353728, 2023).
EIF4E3 also shares sentences with these, for which no sentence is quoted: acute myeloid leukemia (1 paper); autoimmune disease (1); bladder cancer (1); breast adenocarcinoma (1); cyst (1); developmental delay (1); diabetes (1); kidney adenocarcinoma (1); liver fibrosis (1); pemphigus foliaceus (1); pterygium (1); urothelial carcinoma (1).